MDM4 (MDM4 regulator of p53)
Description:
Inhibits degradation of MDM2.
Synonyms: MDMX; HDMX; BMFS6; MRP1
Tractability: Small molecule: a structure with a bound ligand is known; a high-quality ligand is known. PROTAC: UniProt records ubiquitination sites on it; ubiquitination databases record sites on it; its protein half-life has been measured; a small molecule that binds it is known.
Gene: Protein-coding gene on chromosome 1 (204,516,369 to 204,558,120, forward strand). Ensembl gene ENSG00000198625.
Subcellular location: Nucleus; Cytoplasm
Subcellular location (Human Protein Atlas): Nucleoplasm
Pathways (Reactome):
Cellular responses to stimuli: Oncogene Induced Senescence; Oxidative Stress Induced Senescence
Metabolism of proteins: Ub-specific processing proteases
Gene Ontology:
Molecular function: enzyme activator activity; enzyme binding; protein binding; zinc ion binding
Biological process: cellular response to hypoxia; negative regulation of DNA-templated transcription; negative regulation of protein catabolic process; negative regulation of transcription by RNA polymerase II; protein stabilization; protein-containing complex assembly; atrial septum development; atrioventricular valve morphogenesis; endocardial cushion morphogenesis; heart valve development; negative regulation of cell population proliferation; ventricular septum development; negative regulation of apoptotic process; protein-containing complex organization; regulation of cell cycle; regulation of cell population proliferation
Cellular component: cytoplasm; nucleoplasm; nucleus; transcription repressor complex
Genetic constraint (gnomAD): Loss-of-function variants: 2 observed, 43.03 expected, observed/expected ratio (o/e) 0.0465, 90% interval 0.018 to 0.15. The upper end of that interval is the gene's LOEUF score, 0.15, which puts it in group 1 of 6, group 1 being the genes least tolerant of losing a copy. Missense variants: 331 observed, 479.67 expected, observed/expected ratio (o/e) 0.69, 90% interval 0.63 to 0.76. Synonymous variants: 158 observed, 166.93 expected, observed/expected ratio (o/e) 0.95, 90% interval 0.83 to 1.08.
Gene-disease validity (ClinGen):
ClinGen rates the evidence that MDM4 causes each of these diseases.
bone marrow failure syndrome 6 (autosomal dominant): Moderate.
Homologues: Orthologues: chimpanzee MDM4 (99% identical), macaque MDM4 (97% identical), dog MDM4 (94% identical), pig MDM4 (92% identical), rabbit MDM4 (90% identical), guinea pig MDM4 (86% identical), mouse Mdm4 (84% identical), rat Mdm4 (84% identical), zebrafish mdm4 (49% identical), tropical clawed frog mdm4 (47% identical). Paralogues in human: MDM2 (32% identical).
Diseases named in the same sentence as MDM4 in open-access papers:
MDM4 is named in the same sentence as 171 diseases in open-access papers, as found by Europe PMC text mining. Sharing a sentence is not in itself a finding about the gene and the disease. The quoted sentences say what the papers report.
breast carcinoma (93 papers, 2008 to 2025). "These aberrations highlighted well-known breast cancer-associated genes, such as MDM4, ZNF595, FGFR4, HIST1H1B, TPD52, DECR1, GRB7, and JUP55." (PMID 40162205, 2025). "The MDM4 rs11801299 GA genotype and A allele were associated with increased risk to the breast cancer." (PMID 36831624, 2023). "Previous research studies have not extensively elucidated the correlation of genotypes and allele variations of the PI3K, AKT-1, KLF-14, MDM4 and miRNAs 27a, miR-196a genes with the predisposition of Breast cancer in Saudi Arabia." (PMID 36831624, 2023). "In the recessive inheritance model, there was a significant protective effect between the MDM4 (GG + GA) and MDM4 -AA genotypes that reduced breast cancer susceptibility (OR = 0.46 (CI = 0.2598–0.8326), RR = 0.64 (0.4561–0.9060), and p = 0.010)." (PMID 36831624, 2023). "Our findings showed a strong association between the MDM4-GA genotype and increased breast cancer patient susceptibility in the codominant model, with OR = 2.08 (CI = 1.1509–3.771), RR = 1.48 (1.0492–2.0918), and p = 0.015." (PMID 36831624, 2023). "Strong association was reported between the PI3K-AKT signaling pathway genes and KLF 14-AA, MDM4-GA, miR27a-GG and miR-196a-CT gene variants with the breast cancer susceptibility and progression." (PMID 36831624, 2023). "The dominant inheritance model showed a strong association between the MDM4-GG and (GA + AA) genotypes, which increases breast cancer susceptibility (OR = 2.15 (CI = 1.2010–3.8487), RR = 1.51 (1.0747–2.1247), and p = 0.010)." (PMID 36831624, 2023). "In our study we investigated the MDM2 (rs2279744, rs937283, rs937282) and MDM4 (rs1380576, rs4245739) single nucleotide polymorphisms in 100 Lithuanian breast cancer patients." (PMID 33669778, 2021). "Five SNPs across MDM2 (rs2279744, rs937283, rs937282) and MDM4 (rs1380576, rs4245739) genes were evaluated for associations with breast cancer phenotype." (PMID 33669778, 2021). "Mitogenic signaling, through the Ras-MAPK pathway is linked to elevated MDM4 expression levels, at least in some cancers e.g. breast cancer line MCF-7." (PMID 30689920, 2019). "We also find an association between the presence of MAGE-A and increased MDM4 levels in primary breast cancer, suggesting that MAGE-A-dependent control of MDM4 levels has relevance to cancer clinically." (PMID 26001071, 2015). "In these contexts the observed association between MAGE-A expression and increased MDM4 levels in primary breast cancer is quite striking and suggestive of a mechanistic link between these proteins during cancer development." (PMID 26001071, 2015). "We conclude, MDM4 SNP34091 status to be associated with reduced risk of breast cancer, in particular in individuals carrying the MDM2 SNP309GG genotype, but not to be associated with either lung‐, colon‐ or prostate cancer." (PMID 26471763, 2015). "Stratifying according to MDM2 SNP309 status, we observed a reduced risk for breast cancer related to MDM4 SNP34091CC among individuals harboring the MDM2 SNP309GG genotype (OR = 0.41; 95% CI = 0.21–0.82)." (PMID 26471763, 2015). "When all stages were combined, SNPs rs2290854 and rs6682208 (r2 = 0.84) at 1q32, near MDM4, had combined P-values of association with breast cancer risk of 1.4×10−7 and 4×10−7,respectively." (PMID 23544013, 2013).
breast carcinoma (continued). "We have identified a novel locus at 1q32, containing the MDM4 oncogene, that is associated with breast cancer risk for BRCA1 mutation carriers (P<5×10−8)." (PMID 23544013, 2013). "Only imputed SNP rs12404974, located between PIK3C2B and MDM4 (r2 = 0.77 with rs4951407), was more significantly associated with breast cancer (P = 2.7×10−6) than any of the genotyped SNPs." (PMID 23544013, 2013). "In the present study, we investigated the mutational spectrum of the whole MDM4 coding sequence in a group of German patients with familial breast cancer." (PMID 18279506, 2008). "However, several mutations in MDM4 were reported to be associated with cancers such as breast cancer, endometrial cancer, and stomach cancer." (PMID 36831624, 2023). "MDM4 rs11801299 G > A polymorphisms has been reported to be connected with retinoblastoma susceptibility, risk of gastric cancer in Chinese population, and risk of breast cancer." (PMID 36831624, 2023). "MDM4 rs11801299 G > A was associated with breast cancer predisposition in this study." (PMID 36831624, 2023). "Our results revealed that some SNPs of MDM2 and MDM4 might be significantly associated with the breast cancer characteristics." (PMID 33669778, 2021). "Genetic variations (for example, SNPs) in the MDM2 and MDM4 genes may also be associated with breast cancer." (PMID 33669778, 2021). "We have to admit that this is the first analysis of polymorphisms in the MDM2 and MDM4 genes in relation to the breast cancer clinical characteristics in Lithuania; consequently, a much larger cohort of breast cancer patients would be required to verify our findings." (PMID 33669778, 2021). "In a second meta-analysis of three GWAS including 4,193 ER- breast cancer cases and 35,194 controls, combined with 40 follow-up studies, variants at rs4245739 located in the 3′ region of the mouse double minute 4 homolog (MDM4) oncogene on chromosome 1q32.1 seemed to be specific to TNBC." (PMID 31379942, 2019). "We used the luminal human breast adenocarcinoma cell lines ZR-75-1 and MCF7 as in vitro model systems of ERα-positive breast cancer, and we investigated how loss of ERα expression affected MDM4 gene expression at the protein and mRNA levels, as compared to its effects on MDM2 gene expression." (PMID 26909605, 2016). "While evidence linking SNP34091 status to breast cancer risk has been at variance, we recently found the MDM4 SNP34091AC genotype to be associated with a reduced risk of breast cancer among individuals carrying the MDM2 SNP309GG genotype, a genotype, in general, associated with elevated cancer risk." (PMID 26867771, 2016). "Stratifying according to MDM2 SNP309 status (SNP309TT, SNP309TG, and SNP309GG) we found the MDM4 SNP34091CC genotype (recessive model) to be significantly associated with reduced risk of breast cancer among patients carrying the SNP309GG genotype (OR = 0.41; 95% CI = 0.21–0.82)." (PMID 26471763, 2015). "However, they are not in agreement with a previous smaller candidate-gene study that found an association between a correlated SNP in MDM4 (r2>0.85) and overall breast cancer risk." (PMID 23544013, 2013). "It was therefore tempting to investigate whether activating germ-line mutations exist in the MDM4 coding sequence that could also contribute to breast cancer risk." (PMID 18279506, 2008). "It is unknown, however, whether MDM4 gene alterations play some role in the inherited component of breast cancer susceptibility." (PMID 18279506, 2008). "It is unknown, however, whether the MDM4 gene plays some role in the inherited component of breast cancer susceptibility." (PMID 18279506, 2008).
breast carcinoma (continued). "Results showed that the MDM4 rs11801299 G > A genotype was significantly different in cases in early and grade I stage and cases in advanced and grade II stage of breast cancer." (PMID 36831624, 2023). "The MDM4 rs11801299 G > A genotype frequency was GG (62.60%), GA (34.78%), and AA (2.60%) in breast cancer patients and controls, respectively, and GG (78.26%), GA (20.86%), and AA (0.86%) in controls." (PMID 36831624, 2023). "The MDM4′s rs11801299 G > A SNP was statistically significant (p < 0.03) between breast cancer patients and controls." (PMID 36831624, 2023). "The co-amplification of NUAK2 and MDM4 in breast cancer suggests a potential therapeutic application." (PMID 35523770, 2022). "It has been reported that miR-1307 and miR-127-3p are downregulated in DDP-resistant breast cancer and lung cancer cell, respectively, and, mechanistically, they directly targeted MDM4 and MDM2, promoting DDP-resistance." (PMID 35444536, 2022). "Further, MDM4, a putative target of miR-6087 is reported to increase chemoresistance in breast cancer." (PMID 36703917, 2022). "XI-011 has been reported to inhibit the expression of MDM4 in uveal melanoma, head and neck, and breast cancers." (PMID 36010941, 2022). "The therapeutic potential of targeting MDM4 by decreasing its mRNA expression using XI-011 has been demonstrated across different cancer types, including uveal melanoma and breast cancer cells." (PMID 36010941, 2022). "It has been demonstrated that overexpression or amplification of MDM2 and MDM4 genes are common in many malignancies, including breast cancer." (PMID 33669778, 2021). "Many solid tumors, including gliomas, soft tissue sarcomas, head and neck squamous carcinomas, retinoblastomas, melanomas, breast cancers, and HBs show amplification of the MDM4 gene." (PMID 33536467, 2021). "In line with this, it has been shown that XI-011 treatment in MCF7 breast cancer cells dramatically reduces the binding of RNA Pol II to the MDM4 promoter, and thus the rate of MDM4 transcription." (PMID 33429878, 2021). "Couch and colleagues reported the association of the minor allele of MDM4 SNP rs2290854 with breast cancer risk in mutant BRCA1 carriers, suggesting that this MDM4 variant can be a modifying factor for breast cancer in this mutant background." (PMID 34307167, 2021). "In this study, we demonstrated the antitumor efficacy of ALRN-6924, a dual inhibitor of Mdm4 and Mdm2, in ER+ breast cancer cell line models and identified significant synergy with combination of ALRN-6924 with chemotherapeutic agents." (PMID 33663585, 2021).
breast carcinoma (continued). "Unexpectedly, the SNP34091C variant is associated with increased risk of breast cancer, high-grade ovarian cancer (HGSOC), and prostate cancer suggesting a specific sensitivity of these hormone-dependent cancers to presumably low MDM4 levels." (PMID 34307167, 2021). "For instance, genome-wide association studies performed by the Breast Cancer Association Consortium showed that BRCA2, CHEK2, ESR1, FGFR2, MDM4 and PIK3R3 carry germline variants associated with BC development." (PMID 32210335, 2020). "MDM4 was found highly expressed not only in normal breast epithelial cells but also in most luminal breast cancer." (PMID 32802855, 2020). "The response of malignant melanoma A375 and MCF7 breast carcinoma cells, both overexpressing MDM4, was determined using western blotting." (PMID 32934219, 2020). "Evaluation of SNPs from 3,677 women with TNBC and 4,708 controls supported the association of 25 known breast cancer susceptibility loci, including 2q35, LGR6, MDM4, TERT, ESR1, TOX3, and 19p13.1 with TNBC." (PMID 31379942, 2019). "MDMX (MDM4) is emerging as an important breast cancer (BC) biomarker, and oncoprotein, that can be targeted in combination with its well-known family member MDM2." (PMID 31489110, 2019). "Only two of the CNA events identified in MPA/DMBA-induced tumors occur at a notable rate in human breast cancer; MDM4 is amplified in 25%, and PPM1D is amplified in 10% of human BC." (PMID 31366361, 2019). "Alternatively, in a cisplatin-resistance breast cancer context, the levels of miR-1307 and its target MDM4 were identified to be decisive." (PMID 30689920, 2019). "Lastly, we report that endogenous MDM4 negatively regulates ERα expression and forms a protein complex with ERα in breast cancer cell lines and primary human breast tumor tissue." (PMID 26909605, 2016). "In the present work, we report that ERα expression correlates not only with MDM2 gene expression in primary breast carcinoma samples but also with MDM4 expression." (PMID 26909605, 2016). "The rs4245739 A > C polymorphism was first identified in 40 German patients with familial breast cancer through sequencing the whole coding and flanking untranslated regions of MDM4 gene." (PMID 27687591, 2016). "MDM2 and MDM4 also enhance the tumorigenicity of breast cancer cells in in vitro and in vivo models and are overexpressed in primary human breast cancers." (PMID 26909605, 2016). "Like MDM2, MDM4 also plays a protumorigenic role in human breast cancer cells that are cultured in vitro or in vivo as murine xenografts." (PMID 26909605, 2016).